CD4 (CD4 molecule)
Diseases named in the same sentence as CD4 in open-access papers (continued):
Sharing a sentence is not in itself a finding about the gene and the disease.
leukemia (continued). "It was shown in a non-leukemia model that the FLT3-ITD mutation produces functional DCs without pathogenic side effects but does result in increased DC abundance and moderate effects on CD4+ T cell phenotype." (PMID 38495876, 2024). "CD4−/CD8− and CD4−/CD8+ subtype γδT-LGL leukemia were detected in seven (50%) cases each." (PMID 39161592, 2024). "Interestingly, the combination therapy had minimal impact on the expression of cytotoxic molecules in the leukemia specific CD4 T cells." (PMID 37654482, 2023). "After reviewing the literature and cell experiments, we found that CD4 may have a significant correlation with the cell cycle of leukemia." (PMID 37736548, 2023). "Besides anti-inflammatory functions, Tr1-like CD4+ T cells potentially also control leukaemia by harnessing cytotoxic effector functions that are regulated by Eomes." (PMID 36756120, 2023). "While Eomes+ CD4+ T cells co-transferred with Eμ-TCL1 cells in Rag2-/- mice suppressed leukaemia, Eomes deficient cells failed to do so." (PMID 36756120, 2023). "Importantly, we demonstrated that transduction of an avidity-maturated TCR conferred strong cytotoxicity against WT1-expressing leukemia cells on CD4+ T cells, compared to that of its original TCR." (PMID 36939853, 2023). "Moreover, CD4+ CAR-T cells were recently reported to be the dominant cells for persistent remission in leukemia patients treated with CAR-T cell therapy." (PMID 37228617, 2023). "Similarly, it has been shown that IFN-γ produced by NKT cells was essential for CD4+ T cell activation and antitumor function in a leukemia model." (PMID 37923822, 2023). "Sustained CD4+ reconstitution has been associated with improved OS children with leukemia, independent of cell source." (PMID 37780051, 2023). "Interestingly, while leukemia control was achieved in all animals treated with CD4 CAR-T cells, most animals injected with CD8 CAR-T cells succumbed to the disease." (PMID 36593069, 2023). "A recent study demonstrated that the predominance and persistence of CD4+ T cells could induce decade-long leukemia remission." (PMID 37082269, 2023). "Moreover, upregulation of CD80 and CD86 expression in LEXs more effectively promoted DC maturation, CD4+ T cell proliferation, and Th1 cytokine secretion, thus inducing a stronger leukemia antigen-specific anti-leukemia CD8+ CTL response than LEX alone did." (PMID 36466863, 2022). "In addition, our findings indicated that vaccination with CD4+ TLEX-CD8086 cells induced a potent systemic immune response against leukemia in vivo." (PMID 36466863, 2022). "Then, whether LEXs enriched of leukemia cell antigens could target CD4+ T cells and LEXs-targeted CD4+ T cells could induce strong anti-leukemia immunity or not was still unclear?" (PMID 36466863, 2022). "In addition, mice with leukemia had changes in the T-cell compartment, with higher proportions of CD4+ cells and lower proportions of CD8+ cells." (PMID 35831470, 2022). "Overall, these data suggest that leukemia-antigen specific CD4+ T cells may potentially also contribute to anti-tumoral immunity in leukemia." (PMID 36405718, 2022). "Even though leukemia-antigen specificity of CD4+ T cells have been documented in several independent studies, whether AML antigen–specific Tregs are part of this CD4+ T cell population is still unclear." (PMID 36405718, 2022). "The combination also resulted in a more immature immunophenotype than mutated NRAS alone with a double negative leukemia (CD4− and CD8−), similar to the immunophenotype of the patient X09." (PMID 34230493, 2021). "As yet, endogenous CD4+ and CD8+ T cell responses directed against leukemia-specific antigens (LSA) and leukemia-associated antigens have been detected in chronic phase CML patients — particularly LSA derived from the junctional region of BCR-ABL1, which represent CML-specific neo-antigens." (PMID 34727093, 2021).
leukemia (continued). "The resulting leukemias were further phenotyped using flow cytometry with NRAS(G12D) leukemic thymic cells having a more differentiated CD4+/CD8+ immunophenotype and TCF7-SPI1 + NRAS(G12D) leukemic cells a CD4−/CD8−, (intracellular) CD3+ and CD117+ immature immunophenotype." (PMID 34230493, 2021). "Furthermore, the same group has confirmed the safety and effectiveness of CD4 CAR-NK92 cells against various CD4+ T-cell lymphoma/leukemia cell lines and patient samples." (PMID 34422667, 2021). "We now show that FGFR1 fusion kinase-mediated activation of IRAK1 in SCLL cells leads to increased accumulation of myeloid-derived suppressor cells (MDSCs) in vivo with a concomitant suppression of CD4/CD8 T-cells promoting an immune suppressive microenvironment leading to leukemia development." (PMID 34906138, 2021). "Moreover, a study reported that the human T-cell leukemia/lymphotropic virus-1 is the etiological agent of adult T-cell leukemia, an aggressive and fatal leukemia of CD4+ T lymphocytes." (PMID 32391054, 2020). "CD4+ T cell–derived GrA is dispensable for the beneficial graft-versus-leukemia response." (PMID 32809971, 2020). "Based on our results we hypothesize that IL-15sol secreted by the leukemia cells leads to immunity and long-term survival, because it results in an adaptive long-lasting immune response involving predominantly CD4+ and CD8+ T-cells." (PMID 31856922, 2019). "Furthermore, early CD4+ T cell reconstitution (defined by CD4+ T cell >50 × 106/L within 100 days after UCBT) resulted in better leukemia-free survival (LFS) (HR = 0.24, p = 0.003), improved OS (HR = 0.16, p = 0.0014) with lower NRM (HR = 0.20, p = 0.0072)." (PMID 31739455, 2019). "Interestingly, injection of leukemia cells secreting IL-15sol lead to heightened expansion of CD4+ and CD8+ T-cell populations in the peritoneum compared to IL-15Rc." (PMID 31856922, 2019). "Moreover, Pin1 deletion prevents leukemia progression by reducing Notch3 expression and blocking the expansion/invasiveness of circulating CD4+CD8+ T-cells in N3-ICtg blood." (PMID 30038265, 2018). "Importantly, the CD4-HBZ transgenic model also reported systemic inflammation that contributed to leukemia onset." (PMID 29050201, 2017). "This could be verified with rh sCD4 in electrochemiluminescence experiments as well as with cell surface CD4 on T-leukaemia cell lines and primary cells analysed by flow cytometry." (PMID 28090323, 2016). "The precise role of CD4+CD25-CD69+ T cells in leukemia relapse also requires further exploration and may lead to the discovery of new methods of adoptive immunotherapy." (PMID 24984576, 2014). "In addition, as the frequencies of PD-1+ CD4+ T cells have previously been suggested to affect the development of leukemia, we tested if leukemic progression was altered in a C/EBPα-deficient context." (PMID 24404186, 2014). "Collectively, these findings support previous observations by demonstrating that the accumulation of C/EBPα-expressing PD-1+ CD4+ T cells is a general phenomenon in ageing as well as in leukemia, and therefore implicate C/EBPα as a potential driver of this process." (PMID 24404186, 2014). "However, CD25 is also expressed by CD4+ regulatory T cells, which are important for inducing tolerance that preserves the graft-versus-leukemia effect following transplantation." (PMID 22427961, 2012). "In an antitumor vaccine strategy the choice of the appropriate peptide is crucial and we decided to focus our search on longer, HLA class II binder p190-breakpoint peptides, with the intent mainly to prompt a peptide-specific and possibly leukemia-specific CD4+ T cell response." (PMID 23198152, 2012). "We therefore began our investigation by testing whether siRNA targeting of the various isoforms of 14-3-3 could mitigate Vpr-induced G2,M blockade in the CD4+ Jurkat T cell leukemia line." (PMID 18445273, 2008).
leukemia (continued). "Reg CD4+ T cells appeared to be the most interesting population, as we found a significantly increased fraction of these cells in the spleens at our latest time point after leukemia transplantation and highest frequencies of immune checkpoint receptor expressing cells within this T-cell population." (PMID 39518969, 2024). "Therefore, CD4+ TLEX-CD8086 cells may provide an alternative EXO-based strategy for leukemia treatment, in which CD4+ T cells can easily be harvested from the peripheral blood of a patient and activated in vitro." (PMID 36466863, 2022). "In addition, the frequency of Tregs among CD4+ T cells correlated with leukemia burden." (PMID 34727093, 2021). "Moreover, by stimulation with dendritic cells pulsed with different NPM1-mutated peptide mixtures in a 13-day culture, we were able to expand ex vivo leukemia-specific CD8+ and CD4+ CTLs from four NPM1-mutated AML patients, as well as to prime leukemia-specific responses in three healthy donors." (PMID 34502069, 2021). "However, ASXL1expression showed a strong association with the expression of CD4 surfacemarkers in myeloid cells in leukemia patients (CD4 negative cells had lowerASXL1 expression levels (P = 0.022)." (PMID 33432966, 2021). "Moreover, these B7 gene-modified LEXs, particularly LEX-CD8086, could effectively induce CD4+ T cell proliferation, Th1 cytokine secretion, and an antigen-specific anti-leukemia cytotoxic T lymphocyte (CTL) response." (PMID 32578140, 2020). "These B7 gene-modified LEXs could efficiently promote CD4+ T cell proliferation, stimulate Type I cytokine secretion, and induce an antigen-specific anti-leukemia cytotoxic T lymphocyte (CTL) response, leading to a stronger anti-leukemia protective immunity in vivo." (PMID 32578140, 2020). "Thus, the feasibility of T cell therapy based on the adoptive infusion of WT1332-specific TCR-transduced CD4+ T cells could be employed for leukemia immunotherapy." (PMID 30622438, 2019). "Mice that had received LV15sol-expressing leukemia cells had significantly higher numbers of CD4+ cells compared to all other groups, whereas significantly elevated numbers of NK1.1+ cells could be found in mice that had received LV15Rc-expressing leukemia compared to all other groups." (PMID 31856922, 2019). "Similarly, the finding of increased long‐term CD4 concentration for patients with leukemia could be due to these patients receiving full myeloablative conditioning, leaving more space for donor T‐cell expansion." (PMID 28074473, 2017). "Therefore, the frequency of CD4+CD25-CD69+ T cells could represent a suitable parameter to predict the incidence of leukemia relapse after transplantation." (PMID 24984576, 2014). "The proportions of CD4+, CD8+ and regulatory T cells were found to be unaffected by SLAMF6 expression on the leukemia cells." (PMID 41044242, 2025). "In a syngeneic murine model of TCF3::PBX1 leukemia, an upregulation of PD-1, TIM-3, and LAG3 on CD4+ and CD8+ T cells was observed in the presence of leukemia." (PMID 40503229, 2025). "As anticipated, JAKi co-treatment suppressed in vivo CAR T cell activity with delayed leukemia clearance compared to TSLPRCART and vehicle treatment and led to preferential decrement in CD4+ T cell numbers." (PMID 39681640, 2025). "As CB-8F4CAR-iNK T cells are predominantly CD4+, we carefully evaluated their cytolytic activity against PR1/HLA-A2+ or αGalCer/CD1d+ leukemia and compared those with AD-8F4CAR-iNK T cells derived from multiple donors." (PMID 40519924, 2025). "A kidney biopsy was performed, revealing an atypical interstitial T-cell infiltrate with diffuse expression of CD4, CD8, and TdT, raising concern for T-cell acute lymphoblastic lymphoma (instead of leukemia) (T-ALL/LBL)." (PMID 41445717, 2025). "AML cell-derived extracellular vesicles (EVs) inhibit the activity of CD4+ T cells by carrying immune suppressive factors, such as PD-L1, TGF-β1 or miRNA, thereby promoting immune evasion in leukemia." (PMID 40008144, 2025).
leukemia (continued). "Cells with lymphoid markers were also present in the transcriptionally defined leukemia cells, but in smaller proportions, including CD19+/CD22+/CD30+ cells (5.96%) CD19+/CD22+/CD45+ cells (5.49%), CD3+/CD5+/CD7+ cells (4.45%), and CD3+/CD4+/CD5+ cells (0.4%)." (PMID 39294124, 2024). "The overall (slightly) increasing frequencies of IFN-γ-producing CD4, CD8, CIK, and iNKT cells of the innate immune system were seen suggesting an in vivo production/activation of (potentially leukemia-specific) cells." (PMID 39769232, 2024). "Other studies have shown that CD4+ CAR T cells display superior proliferation and antitumor function compared to CD8+ cells in GBM, leukemia, and pleural tumor models." (PMID 39521782, 2024). "We then attempted to achieve a preliminary exploration of the pathogenesis of leukemia through the study of five prognostic genes (TNF, CXCR3, CD4, PIK3CA and CALR)." (PMID 38671491, 2024). "In a recent study we showed that engrafted SCLL cells suppressed the anti-leukemia immune response through induction of MDSC and subsequent suppression of CD4 + and CD8 + cells, to ensure leukemia development." (PMID 38730491, 2024). "The frequencies of CD103+CD3+, CD103+CD4+, and CD103+CD8+ T cells were significantly higher in patients with leukemia in CR than in HIs and DN/RR." (PMID 39391310, 2024). "In fact, both TCR-transduced CD4+ T cells effectively lysed WT1332 peptide-pulsed B-LCL and WT1-expressing HLA-DPB1*05:01-positive leukemia cell line, C2F8-CIITA." (PMID 36939853, 2023). "To further explore this observation, we evaluated for alteration of CD4+ and CD8+ T cell infiltration into the leukemia microenvironment." (PMID 36960055, 2023). "To further identify the properties of VC Phf6 + JAK3M511I leukemia cells, we analyzed T-cell surface markers of GFP+ cells (CD4, CD8, CD25, and CD127)." (PMID 34465864, 2022). "We also compared the ability of LEX-CD8086 and CD4+ TLEX-CD8086 cells to induce antileukemia immunity in vivo, i.e., in prophylactic and therapeutic leukemia mouse models." (PMID 36466863, 2022). "In a mouse model of AML, deletional CD4+ and CD8+ T cell tolerance induction is attributed to leukemia antigen presentation by immature antigen-presenting cells (DCs) or splenic CD8α+ dendritic cells." (PMID 36081495, 2022). "In leukaemia, in vivo generation of CD19-CAR T cells selectively in CD4 T cells by using a CD4-targeted lentiviral vector led to the reduction or even complete elimination of CD19-positive cells." (PMID 35572552, 2022). "LEX-CD8086 transfers its intrinsic LAA and molecules and acquired costimulatory CD80 and CD86 molecules to CD4+ T cells, making CD4+ TLEX-CD8086 cells both Th1 cells and APCs capable of inducing efficient leukemia antigen-specific CD8+ CTL response." (PMID 36466863, 2022). "CD28-mediated costimulation was very important in T-cell activation; CD4+CD28+ T cells and CD8+CD28+ T cells mediated graft-versus-leukemia (GVL) effect to prevent relapse, and CD4+CD28+ T cells also mediated protection against infections." (PMID 35936697, 2022). "Primary leukemic cells in DKO mice were frequently low for CD4 and CD8 whereas E2a-/- leukemias were CD4hiCD8hi or contained SP cells." (PMID 35371057, 2022). "With acquired costimulatory molecules, CD4+ TLEX-CD8086 can act as APCs and are capable of directly stimulating the leukemia cell antigen-specific CD8+ CTL response." (PMID 36466863, 2022). "Tregs depletion at an advanced stage of leukemia progression increased the percentage of effector and IFN-γ-positive CD4+ and CD8+ T lymphocytes, significantly elevated IFN-γ concentration and reduced the concentration of IL-10 in the sera." (PMID 35296093, 2022). "The leukemic cells that arise in DKO mice have very dim expression of CD4 and CD8 and express CD25, which distinguishes them from E2a-/- leukemias." (PMID 35371057, 2022).
leukemia (continued). "Recipients of ICN1 transduced HSPCs showed accumulation of GFP+ T cells with CD4+ CD8+ immunophenotype in peripheral blood (PB), organ infiltration and succumb to leukemia." (PMID 34407842, 2021). "Upon leukemia development in the TCL1 AT model, we observed an accumulation of antigen-experienced CD4+ T cells that show signs of activation as measured by CD69 expression." (PMID 33526861, 2021). "Since the observation indicates that CD4+ and CD8+ cells are responsible for the rejection of IRAK1 KO SCLL cells in syngeneic hosts, we investigated the status of these T cells in these leukemia free mice." (PMID 34906138, 2021). "To investigate the impact of this cell type on CLL progression, we transferred CD4+ T cells into Rag2−/− mice, which lack mature B and T cells to exclude the contribution of CD8+ T cells to leukemia control." (PMID 33526861, 2021). "Severely decreased CD4+ T cell count resulting in lower CD4+/CD8+ ratio, persisted briefly after therapy compared to leukemia patients." (PMID 34267757, 2021). "Together, these experiments demonstrate that loss of IRAK1 expression in the tumor cells leads to immunity related tumor clearance where both the activated CD4+ and CD8+ T-cells are directly responsible for suppressing leukemia development." (PMID 34906138, 2021). "At day 21 after leukemia cell transfer, we found a strong depletion of Eμ-Tcl1 cells, endogenous B cells, and CXCR5+CD4+ T cells in the spleens of the mCXCR5 CAR group compared to the control." (PMID 33431832, 2021). "The defective migration of Itk-/- CD8+ and CD4+ T cells likely contributes to the attenuation of GVHD, since these T cells continue to display GVL effects against leukemia cells that were injected intravenously and reside in secondary lymphoid organs." (PMID 33324410, 2020). "To address this, we performed mixed GVHD/GVL experiments where irradiated BALB/c mice received syngeneic or allogeneic HCT with T cells from WT, Gzma–/–, or Gzma–/– CD4+ T cells and WT CD8+ T cells along with GFP+ MLL-AF9 leukemia cells." (PMID 32809971, 2020). "While both CD4 and CD8 T cells showed strong AML reactivity in vitro, only CD4 T cells were able to effectively eliminate leukemia blasts in AML engrafted NOD/SCID/IL2Rγc−/− (NSG) mice." (PMID 32443793, 2020). "On the contrary, we saw significantly higher numbers of GrzB+CD4+ cells and GrzB+CD8+ cells in the peritoneum of mice injected with leukemia cells secreting IL-15sol compared to IL-15Rc." (PMID 31856922, 2019). "We found CB leukemias to show mostly mono/oligoclonal TCR rearrangements with G+C+ leukemias tending to express rearranged TCRG and TCRD when of CD4− CD8− (DN) phenotype, and rearranged TCRB when of CD4+ CD8+ (DP) phenotype." (PMID 31266935, 2019). "Whereas G+C+ leukemias demonstrated a spectrum of CD4/CD8 phenotypes, G+C− leukemias were mostly DP, but did include one DN case (6 DP + 1 DN in total)." (PMID 31266935, 2019). "We also show that CXCR4 surface expression is central to the migratory ability of CD4+CD8+ cells and such an expression is regulated by Notch3 through β-arrestin in human leukemia cells." (PMID 30038265, 2018). "After elucidating the effects of ArtinM on murine CD4+ and CD8+ T cells, we became interested in evaluating its activities towards a T leukemia cell line." (PMID 28665310, 2017). "Here, hsa-miR-450b-5p was already higher expressed in the CD4+CD8+ double positive subset, but showed a further increase in activity in TAL-R rearranged leukemias." (PMID 28801656, 2017). "He tolerated these medications with excellent adherence, and at the time of presentation for leukemia evaluation, his anti-HIV-1 Western blot was positive, with a plasma HIV-1 viral load of 107 copies/ml and a CD4 count of 293 cells/μl (37% of CD3+ cells)." (PMID 29182633, 2017). "CD4+CD8-, CD4+CD8+, CD4-CD8+, and CD4-CD8- phenotypes were observed in 94%, 3%, 0%, and 3% of primary SS cases, respectively, and in 13%, 0%, 87%, and 0% of T-LGL leukemia cases, respectively." (PMID 29262669, 2017).